RNU4-41P (RNA, U4 small nuclear 41, pseudogene)
Gene: Small nuclear RNA gene on chromosome 12 (98,417,896 to 98,418,038, reverse strand). Ensembl gene ENSG00000201296.
Homologues: Orthologues: chimpanzee U4 (91% identical), macaque U4 (89% identical), guinea pig U4 (49% identical), guinea pig U4 (47% identical), rat LOC120102127 (47% identical). Paralogues in human: RNU4-67P (74% identical), RNU4-45P (73% identical), RNU4-7P (73% identical), RNU4-13P (73% identical), RNU4-68P (73% identical), RNU4-76P (72% identical), RNU4-35P (71% identical), RNU4-56P (71% identical), RNU4-58P (71% identical), RNU4-8P (71% identical), RNU4-42P (71% identical), RNU4-84P (71% identical), and 81 more.